GNAI3 (G protein subunit alpha i3)
Description:
Heterotrimeric guanine nucleotide-binding proteins (G proteins) function as transducers downstream of G protein-coupled receptors (GPCRs) in numerous signaling cascades. The alpha chain contains the guanine nucleotide binding site and alternates between an active, GTP-bound state and an inactive, GDP-bound state. Signaling by an activated GPCR promotes GDP release and GTP binding. The alpha subunit has a low GTPase activity that converts bound GTP to GDP, thereby terminating the signal (By similarity). Both GDP release and GTP hydrolysis are modulated by numerous regulatory proteins. Signaling is mediated via effector proteins, such as adenylate cyclase. Inhibits adenylate cyclase activity, leading to decreased intracellular cAMP levels. Stimulates the activity of receptor-regulated K(+) channels. The active GTP-bound form prevents the association of RGS14 with centrosomes and is required for the translocation of RGS14 from the cytoplasm to the plasma membrane. May play a role in cell division. The active GTP-bound form activates the calcium permeant TRPC5 ion channels.
Synonyms: 87U6; ARCND1; ARCODS; HG1A
Tractability: Small molecule: a structure with a bound ligand is known; it has a high-quality binding pocket. Antibody: UniProt places it where antibodies can reach, with high confidence; its Gene Ontology location is reachable by antibodies, with high confidence. PROTAC: ubiquitination databases record sites on it; its protein half-life has been measured; a small molecule that binds it is known.
Target class: Other membrane protein
Gene: Protein-coding gene on chromosome 1 (109,548,584 to 109,600,195, forward strand). Ensembl gene ENSG00000065135.
Subcellular location: Cytoplasm; Cell membrane; Cytoplasm, cytoskeleton, microtubule organizing center, centrosome
Subcellular location (Human Protein Atlas): Centrosome; Principal piece; Basal body; Centriolar satellite; Cytosol; Golgi apparatus; Nucleoli; Nucleoplasm
Pathways (Reactome):
Signal Transduction: Extra-nuclear estrogen signaling; G alpha (i) signalling events; G alpha (s) signalling events; G alpha (z) signalling events; GPER1 signaling
Disease: ADORA2B mediated anti-inflammatory cytokines production
Hemostasis: ADP signalling through P2Y purinoceptor 12
Neuronal System: Adenylate cyclase inhibitory pathway
Gene Ontology:
Molecular function: GDP binding; GTPase activity; protein binding; G protein-coupled receptor binding; G-protein beta/gamma-subunit complex binding; GTP binding; guanyl nucleotide binding
Biological process: adenylate cyclase-inhibiting G protein-coupled receptor signaling pathway; cell division; GTP metabolic process; positive regulation of macroautophagy; adenylate cyclase-modulating G protein-coupled receptor signaling pathway; negative regulation of adenylate cyclase activity; G protein-coupled receptor signaling pathway; signal transduction
Cellular component: centrosome; cytoplasm; cytoplasmic side of plasma membrane; cytosol; endoplasmic reticulum membrane; extracellular exosome; Golgi membrane; lysosomal membrane; membrane; midbody; plasma membrane; Golgi apparatus
Genetic constraint (gnomAD): Loss-of-function variants: 4 observed, 8.22 expected, observed/expected ratio (o/e) 0.49, 90% interval 0.24 to 1.11. That is too few expected variants to judge how well the gene tolerates losing a copy. Missense variants: 55 observed, 87.28 expected, observed/expected ratio (o/e) 0.63, 90% interval 0.51 to 0.79. Synonymous variants: 32 observed, 31.89 expected, observed/expected ratio (o/e) 1, 90% interval 0.76 to 1.35.
Homologues: Orthologues: chimpanzee GNAI3 (100% identical), macaque GNAI3 (100% identical), pig GNAI3 (99% identical), rabbit GNAI3 (99% identical), dog GNAI3 (99% identical), mouse Gnai3 (98% identical), guinea pig GNAI3 (98% identical), tropical clawed frog gnai3 (94% identical), zebrafish gnai3 (91% identical), Caenorhabditis elegans gpa-3 (50% identical), Caenorhabditis elegans gpa-11 (44% identical), Caenorhabditis elegans gpa-2 (43% identical), and 8 more. Paralogues in human: GNAI1 (94% identical), GNAI2 (86% identical), GNAO1 (71% identical), GNAT2 (69% identical), GNAT3 (68% identical), GNAZ (67% identical), GNAT1 (65% identical), GNA14 (52% identical), GNAQ (52% identical), GNA11 (52% identical), GNAL (45% identical), GNA15 (44% identical), and 3 more.